CDK4 (cyclin dependent kinase 4)
Diseases named in the same sentence as CDK4 in open-access papers (continued):
Sharing a sentence is not in itself a finding about the gene and the disease.
tumor (continued). "Endocrine therapy (ET) remains the cornerstone of treatment, but decisions regarding chemotherapy, cyclin-dependent kinase 4 and 6 (CDK4/6) inhibitors, and bone-modifying agents must be tailored to tumour biology, clinical stage, and menopausal status." (PMID 41744876, 2026). "MYC promotes uncontrolled proliferation of tumor cells by activating cyclin-dependent kinase 4 in cell cycle S-phase entry 40 and fuels metabolic reprogramming via aerobic glycolysis or biosynthetic intermediate production." (PMID 41510169, 2026). "Mechanistically, BCR loss impaired mTOR-dependent anabolic control, reducing protein synthesis, while diminished Cyclin D3 abundance sensitized tumor cells to pharmacological CDK4/6 blockade." (PMID 41668618, 2026). "Despite the considerable advancement of CDK4/6 inhibitors in the treatment of BC, tumor resistance to CDK4/6 inhibitors has been globally reported, and there is an urgent need to explore their specific mechanisms." (PMID 41141392, 2026). "Molecular profiling revealed concurrent KRAS and CDK4 amplifications, providing a plausible mechanistic basis for the tumor's high proliferative index and aggressive behavior, and underscoring the biological heterogeneity underlying this rare presentation." (PMID 42222377, 2026). "Growing evidence suggests that enhancement of the tumor immune response contributes to the antitumor activity of CDK4/6 inhibitors (CDK4/6i), but the role of pretreatment tumor immune microenvironment is not clear." (PMID 41748816, 2026). "In NSCLC, CDK4 amplification disrupts the RB pathway and correlates with poor prognosis, reflecting aggressive tumor biology." (PMID 41303594, 2025). "When cyclin D1 expression is reduced, palbociclib binds more strongly to CDK4/6, resulting in a more effective inhibition of tumor cell proliferation." (PMID 40040723, 2025). "These immune effects can be considered indirect, as they primarily result from changes in tumour biology following CDK4/6 inhibition." (PMID 40002156, 2025). "For instance, CDK4/6is can modulate energy metabolism and induce autophagy and senescence in cells, and CDK4/6is have also been shown to be involved in tumor angiogenesis." (PMID 41463246, 2025). "CDK4/6 inhibitors disrupt cell proliferation and tumor growth by blocking the cell-cycle transition from the G1 phase to the S-phase." (PMID 40711480, 2025). "In vivo treatment with CDK4/6 inhibitors increased PD-L1 levels of tumor cells and sensitized ICBs, resulting in tumor regression in mice receiving combined palbociclib and anti-PD-1." (PMID 39998776, 2025). "Our group has also demonstrated that the replication potency of XVir-N-31 is sufficient to induce in combination with cyclin dependent kinases 4/6 inhibitor (CDK4/6i) abscopal anti-tumor effects in a humanized mouse model." (PMID 40251219, 2025). "Previous studies have demonstrated that miR-506 exerts its tumor-suppressive effects by directly targeting the 3′-UTR of CDK4/6, key regulators of the G1/S transition, thereby inducing G1 phase arrest and inhibiting cancer cell proliferation." (PMID 40248198, 2025). "Reprogramming of tumor cells towards kinases such as EGFR, CDK2, and CDK7 has been implicated in resistance to the CDK4/6i palbociclib in ER-positive breast cancer." (PMID 40949156, 2025). "Y5-3, however, effectively downregulated ALK and CDK4, blocking cell cycle progression at the G0/G1 phase, reducing colony formation, and significantly diminishing tumour volume and weight in vivo." (PMID 40793752, 2025). "In various tumor models, CDK4/6 inhibition has been shown to induce a gene expression signature resembling that of interferon-stimulated genes, which is associated with enhanced immunological responses." (PMID 41326426, 2025).
tumor (continued). "Aberrant activation of IFN-γ signaling is also among the mechanisms by which CDK4/6is can impair anti-tumor immunity." (PMID 41463246, 2025). "Our work demonstrates the impact of CDK4/6i or CDK4/6i priming regimens on the induction of Tpex and their connection with anti‐tumor neutrophils." (PMID 40936164, 2025). "Together, these results underscore the potential of Simvastatin as a therapeutic agent for TNBC by selectively targeting G1 phase arrest and CDK4 expression to inhibit tumor cell growth." (PMID 40864776, 2025). "Combining CDK4/6 inhibitor treatment with anti-PD-1 immunotherapy notably enhances tumor regression and significantly improves overall survival in mouse cancer models." (PMID 39851497, 2025). "Extensive preclinical evidence demonstrates synergistic effects between CDK4/6 inhibitors and mitotic signaling pathway inhibitors across multiple tumor models." (PMID 40421216, 2025). "Further in vivo experiments demonstrated that METTL1 overexpression enhances the anti-tumor efficacy of the CDK4/6 inhibitor abemaciclib." (PMID 41562049, 2025). "Its combination with an ERK inhibitor (ERKi) synergistically suppresses the growth of tumor cell lines by counteracting the compensatory upregulation of ERK signals induced by CDK4/6 inhibition." (PMID 40182139, 2025). "Molecular analysis of tumor tissue identified CDK4 amplification and CDKN2A/B deletion in two patients with OS of >37 and 20 months, respectively." (PMID 41050069, 2025). "Emerging evidence suggests that CDK4/6 inhibitors can synergise with ICB by modulating both tumour cell immunogenicity and the microenvironment." (PMID 40563591, 2025). "Additional factors associated with poorer outcomes included liver metastasis, progesterone receptor negativity, high tumor grade, and the concurrent use of fulvestrant with CDK4/6 inhibitors." (PMID 39859134, 2025). "CDK4/6 inhibition enhances tumor immunogenicity by upregulating MHC class I expression on tumor cells, which can improve immune recognition." (PMID 40282469, 2025). "The development of CDK4/6 inhibitors in oncology has primarily focused on their role in tumor suppression by blocking cell cycle progression in cancer cells." (PMID 40277746, 2025). "For example, a CDK4/6 inhibitor, a senescence inducer, enhanced antitumor immunity by increasing the tumor antigen presentation in mouse models of breast carcinoma and other solid tumors." (PMID 40862837, 2025). "Mechanistically, CDK4/6 inhibitors can modify the tumor’s epigenetic landscape to promote immune activation." (PMID 41550427, 2025). "Through blocking the transition from the G1 phase to the S phase (DNA synthesis phase), CDK4/6i inhibit tumor cell proliferation." (PMID 41244784, 2025). "CDK4/6 inhibitors (CDK4/6i) are designed to interrupt cancer cell proliferation by selectively inhibiting these enzymes, leading to cell cycle arrest and subsequent tumor growth inhibition." (PMID 40377782, 2025). "Recent studies have revealed that CDK4/6 inhibitors not only halt cancer cell proliferation but also increase anti-tumor immunity." (PMID 39930131, 2025). "Heatmap clustering of subtype-specific and oncogenic-pathway-related genes revealed that PDTOs from patients 1 and 2 closely mirrored their tumor tissues, particularly in the expression of CDK4, MDM2, and myelocytomatosis oncogene (MYC)." (PMID 41376821, 2025). "Although current studies on CDK4/6is inducing memory T cells are still relatively scarce, such mechanisms shed new light on the application of CDK4/6is in clinical tumor immunotherapy." (PMID 41463246, 2025). "Second, we utilized scRNA-seq to analyze the heterogeneity of tumor cells, distinguishing between resistant and sensitive subpopulations based on their response to CDK4/6 inhibitor therapy." (PMID 40303916, 2025).
tumor (continued). "It proposed for the first time that CDK4/6 inhibitors exhibit a “duality” in activating or inhibiting anti-tumor immunity when interfering with the interferon signaling pathway, inducing cellular senescence, and certain specific immune cell subsets." (PMID 41463246, 2025). "We used exosomes derived from primary BRCA tumor cells for targeted delivery of siTMEM45A in patient-derived xenograft (PDX) mouse models to enhance sensitivity to CDK4/6i." (PMID 39910045, 2025). "In contrast, combining the NEK2i and CDK4/6i resulted in a statistically significant reduction in tumor growth compared to either drug alone." (PMID 39826695, 2025). "Epithelial-mesenchymal transition (EMT) and TGF-β/Smad3 signaling axis dysregulation constitute critical drivers of CDK4/6 inhibitor resistance, enabling tumor cell plasticity and therapeutic evasion." (PMID 40421216, 2025). "This “pharmacologic quiescence” strategy illustrates the broader utility of CDK4/6 inhibition beyond direct tumour targeting." (PMID 40563591, 2025). "While CDK4/6i plus anti‐PD‐1 and similar combination therapies have shown promise in both preclinical and clinical trials, the anti‐tumor efficacy of sequential targeted therapy followed by immunotherapy has been largely overlooked." (PMID 40936164, 2025). "Inhibiting CDK4/6 not only stops the cell cycle but also boosts the body’s ability to fight cancer by changing the immune checkpoints that are built into the tumor." (PMID 41550427, 2025). "The anti-tumor activity of the p21 deleted T cells was improved when they were pre-treated with palbociclib, suggesting that the excess CDK4/6 activity was responsible for the cytotoxic defect." (PMID 40699853, 2025). "In contrast, patients with luminal tumours are typically treated with endocrine therapy and CDK4/6 inhibitors, whereas single-agent paclitaxel is often preferred for triple-negative tumours." (PMID 40806254, 2025). "Combining CDK4/6 inhibitors with PI3K/mTOR inhibitors can significantly slow tumor growth in animal models, suggesting that PI3K/mTOR inhibitors can help restore sensitivity to CDK4/6 inhibitors." (PMID 40303296, 2025). "CDK4/6 inhibitors, suppress tumor proliferation by blocking the G1/S phase transition through competitive binding to the ATP domain of CDK4/6, thereby inhibiting phosphorylation of the retinoblastoma protein (Rb) and inducing irreversible G1 arrest." (PMID 40861811, 2025). "Analyzes of the phenotypes, composition and communication of cell types within the TME revealed the central role of tumor ecosystem-wide signaling in CDK4/6 inhibitor treatment response." (PMID 40032842, 2025). "Tests of the CDK4/6i priming effect showed that the C‐P regimen had stronger anti‐tumor effects than C‐PC in both models, consistently resulting in the most extensive and durable tumor regression." (PMID 40936164, 2025). "This pathway not only supports tumor growth despite CDK4/6 blockade but also contributes to a more aggressive and therapy-resistant phenotype, underscoring the therapeutic potential of dual inhibition strategies targeting both CDK4/6 and IL-6/STAT3 in TNBC." (PMID 41148817, 2025). "Altogether, these findings highlight that a deeper understanding of the crosstalk between CAFs and tumour cells is crucial to identify key mediators of resistance to CDK4/6 inhibitors toward the development of novel therapeutic strategies." (PMID 41388212, 2025). "The improved safety profile of CDK4/6 inhibitors compared with first-generation molecules provides a rationale for their use in the treatment of different tumours, either as monotherapy or in combination with inhibitors of various signalling pathways." (PMID 41388212, 2025). "Inhibiting CDK4/6 is modestly effective at slowing tumor growth, but resistance to monotherapy develops rapidly through numerous mechanisms." (PMID 40723291, 2025).
tumor (continued). "Another study similarly eliminated B-lineage cells in a mouse ovarian cancer model and showed that the synergistic anti-tumor effects of abemaciclib (CDK4/6 inhibitor) and anti-PD-1 therapy were lost in the absence of B cells." (PMID 40723291, 2025). "In this study, we aimed to investigate the sufficiency of RB activation in controlling tumor growth and metastasis in models that are largely resistant to CDK4/6 inhibitors." (PMID 41326426, 2025). "As most of the data on resistance to CDK4/6i derive from analyses of bulk population, to date little is known about the role of intra-tumor heterogeneity." (PMID 40738893, 2025). "Recognizing the significant influence of non-tumor cells in the TME on CDK4/6i response, we examined the composition and transcriptomic profiles in HR+/HER2- BC metastases before and after CDK4/6i treatment." (PMID 39955556, 2025). "Combining CDK4/6 inhibitor treatment with anti-PD-1 immunotherapy enhances tumor regression and improves overall survival in immune-proficient mice bearing colorectal CT26 tumors." (PMID 40282469, 2025). "In conclusion, the combination of INX-315 with CDK4/6 inhibitors presents a promising strategy to extend the therapeutic applicability of INX-315 beyond CDK2-addicted tumor types." (PMID 39924553, 2025). "Other evidence has indicated that CDK4/6 inhibitors can reduce the population of immunosuppressive regulatory T cells (Tregs), which contribute to tumour progression by promoting immunological tolerance." (PMID 41388212, 2025). "To date, no substantial differences have been demonstrated among individual CDK4/6is in their activation of anti-tumor immunity." (PMID 41463246, 2025). "Beyond direct anti-tumor activity, CDK4/6i has also been explored for its ability to reduce chemotherapy-induced myelosuppression and immunosuppression, potentially preserving antitumor immunity." (PMID 40940886, 2025). "Several translational studies using tumor biopsies have demonstrated that neoadjuvant endocrine therapy combined with CDK4/6 inhibition can reduce Ki67 expression and induce cellular senescence." (PMID 39930131, 2025). "There are multiple therapeutic approaches that aim to target MDM2 and CDK4 activity with the aim to restore the intrinsic tumor suppressor cellular response and to terminate oncogenesis." (PMID 40165894, 2025). "Both in vitro and in vivo, the anti-tumor efficacy of CDK4 inhibitor has been found to be superior to that of sorafenib." (PMID 38231074, 2025). "One of the most relevant immune-related effects of CDK4/6 inhibitors is their ability to promote effector T cell infiltration and to enhance their tumour-killing capacity." (PMID 41388212, 2025). "Fig. (1E) shows that LIHC tumor tissue had considerably greater levels of total CDK4 protein expression relative to normal tissue (p<0.001)." (PMID 38231074, 2025). "As a result, CDK4/6 inhibitors hinder cell cycle progression by preventing Rb phosphorylation, thereby halting cells in the G1 phase and suppressing tumor development and expansion." (PMID 41148817, 2025). "Although their combined efficacy with ADT was suboptimal in organoids in this study, CDK4/6 inhibitors have been shown to enhance tumor immune response and increase tumor-infiltrating lymphocytes." (PMID 41041045, 2025). "This underreported compound, which was originally isolated from the marine invertebrate Eudistoma sp., has been documented for its inhibition of cyclin-dependent kinase 4 (CDK4) and anti-tumor effects." (PMID 40076762, 2025). "We found that NIMA-related kinase-6 (NEK6) levels determine the anti-tumor effects of CDK4/6 inhibitors and that NEK6 was a synthetic lethal target of CDK4/6 inhibitors in EC." (PMID 41560755, 2025). "This concept is reinforced by the notion that CDK4 is able to counteract the tumor suppressor activities of TGF-β pathway activation by phosphorylating and inhibiting Smad3, contributing to uncontrolled cell proliferation." (PMID 39800748, 2025).
tumor (continued). "CDK4/6 inhibitors exert dual anticancer effects by directly arresting tumor cell proliferation and enhancing immunogenicity to activate antitumor immunity." (PMID 40421216, 2025). "Myc plays a central role in tumor progression by promoting cell cycle progression, metabolic reprogramming, and resistance to apoptosis, which can amplify resistance to CDK4/6is." (PMID 39955556, 2025). "In this regard, several studies of tumour cells treated with CDK4/6 inhibitors have demonstrated increased expression of cytokines such as CCL5, CXCL9, CXCL10 and IL-15 which are involved in the recruitment of CD8 + T cells." (PMID 41388212, 2025). "Accordingly, our group has shown that combining XVir-N-31 with CDK4/6i enhances its anti-tumor effects by increasing virus production, genome replication, particle formation, and cancer cell-killing, as shown in vitro and in vivo using humanized murine models." (PMID 40251219, 2025). "Early tumor evolution is marked by CDKN2A/B loss and EGFR, platelet-derived growth factor receptor A (PDGFRA), and CDK4 gains." (PMID 40565099, 2025). "This allows CDK4/6 inhibitors to continue inhibiting tumor cell proliferation and maintain long-term therapeutic efficacy." (PMID 41280894, 2025). "Taken together, these findings suggest that CDK4/6 inhibitor-induced senescence can either contribute to tumour suppression or promote therapy resistance and disease relapse, depending on the specific combination therapy employed and the cellular context." (PMID 41388212, 2025). "Within tumor cells, we identified a biomarker panel from BL tumors that is predictive of late disease progression on CDK4/6i treatment in patients with HR+/HER2- mBC, which was successfully validated in 2 independent cohorts." (PMID 39955556, 2025). "Preclinical studies show that inhibition of PI3K signaling or CDK4/6 can sensitize tumor cells to ionizing radiation by impairing DNA damage repair processes and altering cell-cycle distribution, thereby increasing persistent DNA damage and radiosensitivity." (PMID 41280894, 2025). "Given that CDK4/6is can increase the expression of PD-L1 in tumor cells, a large number of studies have investigated the anti-tumor and immune regulatory effects of CDK4/6i sin combination with anti-PD-1/PD-L1 antibodies." (PMID 41463246, 2025). "Preclinical and clinical studies have shown that CDK4/6 inhibitors impair bone marrow function, reducing the production of immune cells essential for effective tumor clearance." (PMID 39930131, 2025). "Persistent or dysregulated STAT3 activation has been shown to drive tumor cell proliferation, apoptosis evasion, and immune modulation, thereby promoting resistance to CDK4/6 inhibitors." (PMID 40303916, 2025). "Palbociclib, a CDK4/6 inhibitor, has been shown to enhance anti-tumor immunity by promoting T cell infiltration and reducing Treg accumulation." (PMID 40826334, 2025). "Consistent with our in vitro findings, continuation of any CDK4/6i significantly attenuated overall tumor growth relative to treatment discontinuation." (PMID 39605351, 2025). "Blocking CDK4/6 can make tumor cells produce more MHC class I and PD-L1 and more chemokines that attract T cells." (PMID 41550427, 2025). "In the context of CDK4/6i, both intrinsic tumor features and acquired molecular alterations influence clinical outcomes, making biomarker development and validation a critical component of ongoing research." (PMID 40940886, 2025). "miR‐206 directly targets CDK6 in the RAS signaling pathway, and its introduction into PM cells inhibits tumor growth; this effect is further enhanced when combined with the cyclin‐dependent kinases 4 and 6 (CDK4/6) inhibitor abemaciclib." (PMID 40904706, 2025). "To further confirm the role of XBP1s in tumor response to CDK4/6 inhibitors plus endocrine therapy, we generated cell‐derived xenograft models using XBP1s‐overexpressing and control MCF7 cells." (PMID 40940685, 2025).